LGALS1 (galectin 1)
Diseases named in the same sentence as LGALS1 in open-access papers (continued):
Sharing a sentence is not in itself a finding about the gene and the disease.
cancer (continued). "These proteins, including AHCYL1, APLP2, CTNN1D, EIF2B1, LGALS1, and SGPL1, play vital roles in maintaining cellular functions such as cell adhesion, protein synthesis, and lipid metabolism, which are often perturbed in cancer cells." (PMID 40090465, 2025). "LGALS1 and BCL2A1 may play roles in promoting cancer in AML, while ELANE may have a significant effect on suppressing cancer." (PMID 38205232, 2024). "CXCL8 and LAPTM5 proteins have been reported to promote cell activity, TMEM156 and LGALS1 proteins enhance cell invasion, VIM and LGALS1 proteins induce cell migration, FABP5 and SRGN proteins activate cancer metastasis, and the DEFB4A protein regulates immunity in human cancers." (PMID 35632763, 2022). "Additionally, SHK has also exerted anti-cancer activity in CRC, that is, SHK stimulates apoptosis and autophagy in CRC via targeting galectin-1/JNK signaling axis." (PMID 35192430, 2022). "LGALS1, NPM1, RACK1, and PERP were upregulated from ductal to cancer cells." (PMID 34326696, 2021). "PROM1, LGALS1, CD44, FUT4 and HOXA10 were identified as hub genes, which were involved in focal adhesion, calcium-dependent phospholipid binding, connective tissue development and transcriptional misregulation in cancer." (PMID 32347296, 2020). "For screening of new glyco-PSs to be used in cancer PDT, the overarching hypothesis is that these dyes adhere to glyco-binding proteins such as galectin-1 and GLUT1 overexpressed in cancer cells, thereby improving the selectivity of the PS for cancer." (PMID 28545086, 2017). "According to several recent studies, Galectin-1 could activate FAK/P13K/ATK signaling, hedgehog signaling, and bind β1 integrin, inducing the EMT process in cancer cells." (PMID 29156810, 2017). "In particular, with enhanced PSC-derived Galectin-1 expression, Vimentin and MMP9 expression increased in the cytoplasm of the stromal area around the PDAC cells and E-cadherin expression decreased on the cancer cell membrane." (PMID 29156810, 2017). "Recently it was shown that galectin-1 (Gal-1) is a functional tissue plasminogen activator (tPA) -receptor participating in PDAC progression with high specificity and strong affinity and therefore provides a promising therapeutic strategy for this cancer." (PMID 27993133, 2016). "Levels of galectin-1 protein and levels of LYAR protein in CRC tissues exhibited a significant correlation calculated by Pearson's correlation, further indicating that LGALS1 is a potential target of LYAR in cancer cells." (PMID 26413750, 2015). "Galectin-1, a product of the LGALS1 locus, induces apoptosis of T-lymphocytes and cancer cells." (PMID 25256425, 2014). "The mRNA expression of galectin-1 and galectin-3 is significantly increased in RCC cancer tissue." (PMID 24708743, 2014). "If albumin and IgG, both of which do not bind galectin-1, are excluded, galectin-1 binds approximately 10–15% of the remaining glycoproteins in healthy sera and up to 40% in cancer sera." (PMID 22028908, 2011). "This is not likely to be functionally significant in serum or plasma itself since there the concentration of galectin-1 dimer is very low (<1 nM, <3 nM (not detected) as confirmed here for 5 of the healthy and cancer samples." (PMID 22028908, 2011). "As a versatile protein, galectin-1 is involved in multiple important life activities, so it is expressed in a variety of cell types, including stromal cells, mesenchymal stem cells, activated T cells, and many other types of cells, not just cancer cells." (PMID 37047471, 2023). "To determine the extent of GAL1 expression in UC and normal tissues, we first examined the LGALS1 mRNA levels in human bladder cancer tissues from the TCGA cohort and GSE32894 data set and our in-house q-PCR analysis of 55 paired normal tissue and cancer specimens (KSCGMH cohort)." (PMID 32225123, 2020). "The Galectin-1 staining intensity was not obviously observed in cancer cells." (PMID 24595374, 2014).
cancer (continued). "The average concentration of galectin-1 bound IgM was slightly lower in cancer sera (not significant), due to a significant decrease (p<0.0005) in the percentage of IgM bound to galectin-1 (mean 37% for healthy sera and 28% for cancer sera)." (PMID 22028908, 2011). "In addition, distinct requirements for DC activity in specific tissue sites by discrete DC subsets in cancer models and T. cruzi infection may also help explain lack of requirement for DC-dependent galectin-1-mediated immune regulation in experimental VL." (PMID 29075269, 2017). "Interestingly, galectin-1 is unlikely to be involved in the uptake of PorGlu4, since a decreased expression of this protein in HCT-116 compared with UM-UC-3 and HeLa cancer cells did not correspond to a proportional decreased uptake." (PMID 28545086, 2017).
infection (52 papers, 2008 to 2025). The state of being infected such as from the introduction of a foreign agent such as serum, vaccine, antigenic substance or organism. "Conversely, elevation of the dormant infection markers, alongside reduction of Galectin-1, carried an increased risk of infection recurrence (22%) within 3 years." (PMID 41387890, 2025). "Here, we investigated the role of galectin-1 in experimental VL caused by infection of C57BL/6 mice with Leishmania donovani." (PMID 29075269, 2017). "The rs4820294/rs2899292 haplotype GG, in association with protection from A(H7N9) infection (OR = 0.26, P = 5.92 × 10−7) correlated to significantly higher levels of LGALS1 mRNA (P = 0.050) and protein expression (P = 0.025) in lymphoblast cell lines." (PMID 25687228, 2015). "Both galectin-1 and -3 have been implicated in increasing target cell infection with human T cell leukemia virus type 1 (HTLV-1)." (PMID 24995007, 2014). "This condition seems to be associated with the evidence that the Lgals1–/– macrophages (and probably other cell types as well) release higher amounts of virus particles at 72 hours post-infection, compared with the WT macrophages." (PMID 25392933, 2014). "We also observed infection-associated up-regulation of transcripts for two galectins, which belong to the C-type lectin family; galectin 1 (+1.5 fold), and galectin 4 (+1.6 fold)." (PMID 21682880, 2011). "We also observed infection-associated up-regulation of transcripts for two other galactose-binding lectins; galectin 1, which is thought to bind gastrointestinal mucins, and galectin 4, which has been shown to be localised to gastric mucous cells in mice." (PMID 21682880, 2011). "Moreover, functional variants in LGALS1 that alter its expression have been associated with differential susceptibility to influenza A(H7N9) infection." (PMID 41041455, 2025). "IFITM1/3 restricts infection of chicken cells by a range of different viruses, including highly pathogenic avian influenza virus, and expression of chicken galectin-1 (encoded by CG-1B) inhibits Newcastle disease virus adsorption and replication in chicken cells in vitro." (PMID 37954617, 2023). "Interestingly, galectin-1 has been proposed to serve as a danger-associated molecular pattern secreted in response to infection inflammation and stress." (PMID 35046919, 2021). "However, the relatively early effects of galectin-1-deficiency during infection also suggest effects of galectin-1 on innate cell activity, although this is unlikely to be on DCs." (PMID 29075269, 2017). "Since syncytia formation is the pathognomonic hallmark of NiV infection, we predict that, in vivo, galectin-1 may reduce pathophysiologic consequences during the course of an infection." (PMID 20657665, 2010). "Galectin-1, with its immunosuppressive profile and region-specific expression in the pediatric gastric mucosa, could serve as a biomarker for early-life infection persistence and for stratifying patients at risk for chronic infection with minimal inflammatory damage." (PMID 40806347, 2025). "Galectin-1 (Gal-1) is also extracellularly released during infection or inflammation, but the secreted extracellular Gal-1 is described as a strong immunosuppressor (e-b), unlike the intracellular Gal-1." (PMID 36672169, 2023). "Zuñiga and colleagues conducted a study to examine the expression and regulation of Galectin-1 (Gal-1) within the B-cell compartment, employing T. cruzi (Tulahuen strain) infection as a natural model for in vivo B-cell activation." (PMID 38067100, 2023). "In the presence of galectin-1, infection of Syncytin-2-pseudotyped viruses augmented for all cell lines." (PMID 38140682, 2023). "Given that H-1PV requires S-phase factors expressed in proliferating cells for a productive infection, we evaluated the proliferation of LGALS1 KO versus Control cells." (PMID 35632759, 2022). "Two hours post-infection, fluorescence was significantly lower in LGALS1 KO cells than in Control cells." (PMID 35632759, 2022).
infection (continued). "More recently, galectin-1 has been shown to inhibit the infection of cardiac cells exposed to T. cruzi in culture, using two strains of the parasite with different genetic backgrounds." (PMID 35046919, 2021). "An enhancing effect occurs when galectin-1 binds during the initial phase of viral attachment to the target cell membrane, whereas an inhibitory effect occurs post-infection when galectin-1 targets NiV-F expressed on the cell membrane." (PMID 32019182, 2020). "There were 10 common downregulated transcripts with a further six being unique to the synchronised infection (i.e., Hist4h4, 2900010M23Rik, Churc1, Rps15a, Lgals1, S100a16)." (PMID 31546628, 2019). "Galectin-1 KO mice displayed increased parasitism and mortality upon infection with the Tulahuen strain, classifying it as a PRG." (PMID 30559742, 2018). "A small subpopulation of B cells was found to express galetin-1 during established infection in both the liver and spleen, although this population and galectin-1 expression was more prominent in the spleen." (PMID 29075269, 2017). "Given that enhanced control of parasite growth in the liver was observed early after infection, we next examined galectin-1 expression on immune cell populations at day 14 p.i.." (PMID 29075269, 2017). "Galectin-1 has been demonstrated to control pathogens infection through inhibiting microbial activity and inducing apoptosis in host cell." (PMID 27240351, 2016). "Therefore, the higher LGALS1 expression level of rs4820294/rs2899292 haplotype GG may represent the molecular underpinning for its genetic association with the resistance to A(H7N9) infection." (PMID 25687228, 2015). "The percentage of female Lgals1-/- mice that survived acute infection with T. cruzi Tulahuén strain was significantly lower (P = 0.0008) and the mean survival time was shorter (P = 0.0127) compared to their WT counterpart." (PMID 26451839, 2015). "In this study, the identification of rs4820294/rs2899292 haplotype GG and rs4820294 as eQTLs for LGALS1 in LCLs and primary human cells adequately substantiates their genetic association with the susceptibility to A(H7N9) infection." (PMID 25687228, 2015). "Although galectin-1 concentrations in our infection experiments were higher than the measured levels from the supernatant of infected cells, in vivo conditions are likely to differ from our cell culture settings." (PMID 19032754, 2008). "Infection of Jurkat E6.1 cells by the pseudotyped virions was increased by 1.6 fold in the presence of 2 μM of galectin-1, an increase which was statistically significant (F = 6.764, p = 0.0138)." (PMID 19032754, 2008). "The infection of PBMCs by pseudotyped virions was increased by 1.8 fold in the presence of 4 μM of galectin-1." (PMID 19032754, 2008). "A more physiological model was also used to study the impact of soluble galectin-1 on infection by HTLV-I pseudotyped virus." (PMID 19032754, 2008). "Notably, Galectin-1 (Gal-1) normally promotes immune tolerance and limits inflammation, so the downregulation of Gal-1 in joint replacements with a dormant infection suggests an ongoing antibacterial response." (PMID 41387890, 2025). "In addition to glucocorticoids, there are other factors such as galectin-1, prolactin, progesterone, and IL-10 have been reported to inhibit infection-induced inflammatory responses in the intrauterine tissues." (PMID 39290694, 2024). "It was reported that galectin-1 substantially attenuated CD4+ T cells, neutrophils, and CD45+ T infiltration as well as T helper (Th) 17 response, which diminished severe corneal immunoinflammatory impairment caused by infection of Pseudomonas aeruginosa." (PMID 37047471, 2023). "The dual roles of galectin-1 in infection are discussed in the following three sections." (PMID 37047471, 2023).
infection (continued). "There was approximately ~8 ng ml-1 of galectin-1 in the conditioned medium from hVECs before the infection, which decreased by 40% at 1 min post-infection, presumably via binding to the parasite, then increased up to ~80% of the original level at 30- and 60 min post-infection." (PMID 36595499, 2023). "Quantification of galectin-1 and galectin-3 secreted from hVECs and HeLa cells before and post-infection revealed that both galectins were secreted at much higher levels from hVECs than HeLa cells, explaining why the swarming phase was less observed in HeLa cells on infection." (PMID 36595499, 2023). "Calculating the differentially expressed genes revealed that genes such as Nkg7, Lgals1, Pdcd1, and Ccr2 were significantly upregulated in expanded cells in at least one infection condition and demonstrated consistent trends in expression for all infection groups." (PMID 35185882, 2022). "Given that laminins containing the γ1 chain play determinant roles in H-1PV attachment at the cell surface as well as in H-1PV cell entry, we asked whether siRNA-mediated silencing of LAMC1 in LGALS1 KO cells would further decrease H-1PV infection." (PMID 35632759, 2022). "Galectin-1, a prototype member of the galectin family, is highly expressed by different cell types, including immune cells, epithelial cells, endothelial cells, and adipocytes, at sites of infection and inflammation." (PMID 35046919, 2021). "Apart from proteins discussed in more detail below, other accumulated proteins upon infection included galectin 1 and macrophage-capping protein, and less abundant endoplasmin, GTP-binding nuclear protein RAN, peptidyl-prolyl cis-trans isomerase FKBP4, and adenine phosphoribosyltransferase." (PMID 31708904, 2019). "However, subsequent studies with infection of Galectin-1 with the RA strain showed reduced parasitism and mortality, which is not a PRG profile." (PMID 30559742, 2018). "However, we found galectin-1-mediated suppression of effector cytokine production by hepatic Th1 cells following infection." (PMID 29075269, 2017). "The result of the dual interaction with galectin-1 and -3 is a subdued mucosal environment, less hostile to the parasite, which is in line with clinical findings of the persistent and often silent/asymptomatic nature of this infection." (PMID 26589797, 2016). "A recent study indicated galectin-1 shows inhibitory effect on infection of dengue virus type-1." (PMID 27240351, 2016). "Therefore, the role of galectin-1 needs to be further investigated under infection of dengue virus type I in clinic." (PMID 27240351, 2016). "Our findings suggest that in affected individuals, the A(H7N9) infection may be attributed to low levels of LGALS1 in the respiratory tract." (PMID 25687228, 2015). "However, infection rates of galectin-1-/- EV71 viruses dramatically dropped from 55.6% to 4.6% after heat treatment." (PMID 25706563, 2015). "Although mice from both lineages displayed similar overall mortality rate, Lgals1–/– mice began to succumb earlier than WT mice: within the first 4 days post-infection, almost 60% of Lgals1–/– mice died, while 90% of WT mice survived up to 5 days past challenge." (PMID 25392933, 2014). "In mammals, Galectin 1 cross-links the N-glycans displayed in the envelope proteins of Nipah and Hendra viruses (paramyxoviruses that induce syncytia in infected cells), directly blocking cell infection and cell-cell fusion." (PMID 22428080, 2012). "In the present study, we have focused on galectin-1, mainly because of its capacity to mediate cell-to-cell contact but also because this protein is expressed by activated T cells and cells from lymphoid tissue, a major site of infection by HTLV-I." (PMID 19032754, 2008). "Hence, these results show that extracellular galectin-1 increases infection of a T cell line and PBMCs by free HTLV-I gp46-pseudotyped viruses and that this increase relies on the binding of cell/virus surface carbohydrates by the galectin-1 CRD." (PMID 19032754, 2008).